ARHGEF35 (Rho guanine nucleotide exchange factor 35)
Synonyms: ARHGEF5L; FLJ43692; CTAGE4
Tractability: No criterion of Open Targets' tractability assessment is met for any kind of drug.
Gene: Protein-coding gene on chromosome 7 (144,182,888 to 144,195,879, reverse strand). Ensembl gene ENSG00000213214.
Pathways (Reactome):
Signal Transduction: G alpha (12/13) signalling events; NRAGE signals death through JNK
Genetic constraint (gnomAD): Loss-of-function variants: 1 observed, 1.07 expected, observed/expected ratio (o/e) 0.94, 90% interval 0.26 to 1.89. That is too few expected variants to judge how well the gene tolerates losing a copy. Missense variants: 108 observed, 137.96 expected, observed/expected ratio (o/e) 0.78, 90% interval 0.67 to 0.92. Synonymous variants: 47 observed, 56.67 expected, observed/expected ratio (o/e) 0.83, 90% interval 0.65 to 1.06.
Homologues: Orthologues: Caenorhabditis elegans ephx-1 (14% identical). Paralogues in human: ARHGEF5 (30% identical), ARHGEF19 (19% identical), NGEF (15% identical), ARHGEF15 (12% identical), ARHGEF26 (11% identical), ARHGEF16 (11% identical).
Diseases named in the same sentence as ARHGEF35 in open-access papers:
ARHGEF35 is named in the same sentence as 1 disease in open-access papers, as found by Europe PMC text mining. Sharing a sentence is not in itself a finding about the gene and the disease. The quoted sentences say what the papers report.
cancer (1 paper, 2025). A tumor composed of atypical neoplastic, often pleomorphic cells that invade other tissues. "Given the nascent state of research on ARHGEF35, its precise molecular functions and prognostic impact in AML and other cancers remain incompletely defined, warranting further investigation." (PMID 40748972, 2025).